UGT2A1 (UDP glucuronosyltransferase family 2 member A1 complex locus)
Description:
UDP-glucuronosyltransferase (UGT) that catalyzes phase II biotransformation reactions in which lipophilic substrates are conjugated with glucuronic acid to increase the metabolite's water solubility, thereby facilitating excretion into either the urine or bile. Essential for the elimination and detoxification of drugs, xenobiotics and endogenous compounds. Catalyzes the glucuronidation of endogenous steroid hormones such as androgens (testosterone and epitestosterone) and estrogens (estradiol and epiestriol). Contributes to bile acid (BA) detoxification by catalyzing the glucuronidation of BA substrates, which are natural detergents for dietary lipids absorption. Shows a high affinity to aliphatic odorants such as citronellol as well as olfactory tissue specificity, and therefore may be involved in olfaction. Shows a potential role in detoxification of toxic waste compounds in the amniotic fluid before birth, and air-born chemical after birth.
Synonyms: UDPGT2A1
Tractability: Antibody: UniProt predicts a signal peptide or a membrane-spanning region.
Target class: Enzyme; Transferase
Safety:
Unwanted effects reported when the protein is acted on. In parentheses: how it was acted on, where the effect was seen, and who reports it.
drug toxicity (source: ClinPGx)
Gene: Protein-coding gene on chromosome 4 (69,588,417 to 69,653,249, reverse strand). Ensembl gene ENSG00000173610.
Subcellular location: Membrane; Endoplasmic reticulum membrane
Pathways (Reactome):
Drug ADME: Aspirin ADME
Metabolism: Glucuronidation
Gene Ontology:
Molecular function: glucuronosyltransferase activity; UDP-glycosyltransferase activity
Biological process: bile acid metabolic process; response to symbiont; sensory perception of chemical stimulus; xenobiotic metabolic process
Cellular component: endoplasmic reticulum membrane; membrane
Genetic constraint (gnomAD): Loss-of-function variants: 59 observed, 45.46 expected, observed/expected ratio (o/e) 1.3, 90% interval 1.05 to 1.61. The upper end of that interval is the gene's LOEUF score, 1.61, which puts it in group 6 of 6, group 1 being the genes least tolerant of losing a copy. Missense variants: 643 observed, 595.14 expected, observed/expected ratio (o/e) 1.08, 90% interval 1.01 to 1.15. Synonymous variants: 225 observed, 202.22 expected, observed/expected ratio (o/e) 1.11, 90% interval 1 to 1.24.
Homologues: Orthologues: macaque UGT2A1 (91% identical), mouse Ugt2a1 (81% identical), zebrafish ugt2b1 (48% identical), zebrafish ugt2a7 (48% identical), zebrafish ugt2b5 (48% identical), zebrafish ugt5a1 (37% identical), zebrafish ugt5a2 (36% identical), zebrafish ugt5b4 (36% identical), zebrafish ugt5b2 (35% identical), zebrafish ugt5c1 (35% identical), zebrafish ugt5c2 (35% identical), zebrafish ugt5c3 (34% identical), and 94 more. Paralogues in human: UGT2A2 (71% identical), UGT2A3 (55% identical), UGT2B4 (55% identical), UGT2B17 (54% identical), UGT2B7 (54% identical), UGT2B15 (53% identical), UGT2B11 (51% identical), UGT2B10 (51% identical), UGT2B28 (51% identical), UGT1A1 (38% identical), UGT1A6 (38% identical), UGT1A4 (37% identical), and 9 more.
Diseases named in the same sentence as UGT2A1 in open-access papers:
UGT2A1 is named in the same sentence as 13 diseases in open-access papers, as found by Europe PMC text mining. Sharing a sentence is not in itself a finding about the gene and the disease. The quoted sentences say what the papers report.
COVID-19 (8 papers, 2022 to 2025). A disease caused by infection with severe acute respiratory syndrome coronavirus 2. "A genome-wide association study (GWAS) of COVID-19-related loss of smell and taste of self-reported participants revealed a significant locus in the vicinity of the UGT2A1 and UGT2A2 genes." (PMID 36835589, 2023). "By applying COVIDanno, we identified multiple important genes associated with COVID-19 symptoms, such as UGT2A1, FGF12." (PMID 37497545, 2023). "In particular, UGT2A1 has been reported to associate with COVID-19-related loss of smell and taste in multiple studies." (PMID 37497545, 2023). "Previous studies, including genome-wide association studies (GWAS), have identified genetic variants near the UGT2A1 and UGT2A2 genes that are linked to anosmia in COVID-19 patients." (PMID 39767184, 2024). "Interestingly, UGT2A1 and UGT2A2 have recently been implicated in COVID-19-associated loss of smell and taste." (PMID 38098019, 2023). "While the specific function of UGT2A1/UGT2A2 is not clear in COVID-19-related loss of smell, this study provides a first genetic link between the physiology of infected cells and subsequent functional olfactory impairment." (PMID 36835589, 2023). "Although we have a clue that the UGT2A1 locus, and, therefore, the UDP glycosyltransferase, is involved in the ethnic differences in COVID-19-related olfactory dysfunction, the mechanism remains unclear." (PMID 36766771, 2023).
Anosmia (4 papers, 2024). An inability to perceive odors. "Both UGT2A1 and UGT2A2 are enriched in the olfactory epithelium and govern odorant metabolism, and it is of interest for future study to delineate the mechanisms underlying their contributions to anosmia and ageusia." (PMID 38846354, 2024). "Besides, a multi-ancestry GWAS has identified a correlation between the UDP glucuronosyltransferase family 2 member A1/A2 (UGT2A1/UGT2A2) and COVID-19-related anosmia and ageusia." (PMID 38846354, 2024). "We selected UGT1A1 as a target because no SNP variants associated with anosmia have been identified in UGT1A1 and it is a homolog of UGT2A1 implicated in olfactory function." (PMID 39767184, 2024).
cholestasis (1 paper, 2016). Impairment of the bile flow caused by obstruction within the liver, or outside the liver in the bile duct system. "Consistently, nine genes in the fatty acid metabolism, phospholipidosis and steatosis pathways including Acot2, Ugt2a1, Cd36 and Retn were upregulated in the cirrhotic liver post SPION injection accompanied with elevated Tgfb1 and sodium bile acid cotransporter (Slc10a1) of the cholestasis pathway." (PMID 27357559, 2016).
ovarian carcinoma (1 paper, 2019). A malignant neoplasm originating from the surface ovarian epithelium. "In summary, this study reports, for the first time, an association between EGFR and UGT2A1/2 variants with ovarian cancer risk in AA women." (PMID 31001917, 2019).
renal carcinoma (1 paper, 2021). A carcinoma arising from the epithelium of the renal parenchyma or the renal pelvis. "The downregulation of UGT2A1 was also seen in the Jones Renal cancer dataset." (PMID 34503303, 2021).
cancer (2 papers, 2014 to 2021). A tumor composed of atypical neoplastic, often pleomorphic cells that invade other tissues. "For example, UGT2A1 was downregulated in 4 cancers (HNSC, KICH, KIRC, KIRP) but upregulated in LUSC." (PMID 34503303, 2021). "A number of known and previously unknown oncogenes were identified, some of which have already been reported to be associated with cancer, including: ADCY8, ZFAT, BAI1, PTK2, FBXL6, FOXH1, HSF1, and UGT2A1." (PMID 25372838, 2014).
UGT2A1 also shares sentences with these, for which no sentence is quoted: Ageusia (1 paper); gout (1); malaria (1); ovarian disease (1); prostate carcinoma (1); steatosis (1); type-2 diabetes (1).